IL13RA1 (interleukin 13 receptor subunit alpha 1)
Diseases named in the same sentence as IL13RA1 in open-access papers (continued):
Sharing a sentence is not in itself a finding about the gene and the disease.
helminth infections (1 paper, 2014). "The ligands of the IL13Rα1, IL13 and IL4, are components of type II immune responses, which characterize allergic reactions and helminth infections, and, interestingly, are also involved in the susceptibility of DA neurons to death by oxidative stress." (PMID 25525298, 2014).
inflammatory bowel disease (1 paper, 2018). A spectrum of small and large bowel inflammatory diseases of unknown etiology. "Given the differential expression of miRs in inflammatory bowel disease potentially targeting IL13RA1, and the importance of IL-13 in the gut mucosa, we set out to investigate the expression levels of IL13RA1 in UC and the possible role of miRs in its regulation." (PMID 29438285, 2018).
leukemia (1 paper, 2018). A malignant (clonal) hematologic disorder, involving hematopoietic stem cells and characterized by the presence of primitive or atypical myeloid or lymphoid cells in the bone marrow and the blood. "Moreover, we assessed which components of the IL4R complexes that are expressed in c-Kit+ leukemia cells, and found that the Il4ra and Il2rg are expressed, but not Il13ra1." (PMID 28819278, 2018).
lung adenocarcinoma (1 paper, 2022). A carcinoma that arises from the lung and is characterized by the presence of malignant glandular epithelial cells. "Human lung adenocarcinoma cell line A549 endogenously expresses moderate levels of IL13Rα1 with no detectable IL13Rα2 or IL4Rα." (PMID 35939683, 2022).
lung fibrosis (1 paper, 2018). "It was also recently demonstrated that IL13Rα1 expression is diminished in lung sections from patients with interstitial pulmonary fibrosis." (PMID 29438285, 2018). "This work showed that IL13RA1 may have a protective role in lung injury and repair, as Il13ra1 knock out mice display an increase in bleomycin-induced lung fibrosis." (PMID 29438285, 2018).
malaria (1 paper, 2013). Malaria is a serious and sometimes fatal disease caused by a parasite that commonly infects a certain type of mosquito which feeds on humans. "As such, the presence of the TA haplotype could be altering the gene-gene interactions of IL-13 and IL-13Rα1, thereby promoting enhanced IL-4 production leading to inhibition of erythropoiesis in children with malaria." (PMID 23521898, 2013).
medulloblastoma (1 paper, 2002). A malignant, invasive embryonal neoplasm arising from the cerebellum. "Our present results confirm those observations and demonstrate that medulloblastoma cell lines also express IL-4Rα and IL-13Rα1 chains in all cell lines tested." (PMID 11870521, 2002).
meningioma (1 paper, 2021). A generally slow growing tumor attached to the dura mater. "In addition, the expression of IL4Rα and IL13Rα1 were increased in meningioma compared with normal brain tissue and were higher in invasive pituitary adenoma compared to non-invasive pituitary adenoma." (PMID 33419470, 2021).
mesothelioma (1 paper, 2024). A usually malignant and aggressive neoplasm of the mesothelium which is often associated with exposure to asbestos. "We note that the increased expression of NDUFA1, TES and IL13RA1 associated with poor survival outcome in the TCGA mesothelioma cohort contrasted with the literature." (PMID 38694815, 2024).
nicotine addiction (1 paper, 2026). "Future studies are needed to fully elucidate the role of IL-13/IL-13Rα1 signaling in the development of nicotine addiction and its possible translational relevance." (PMID 40775068, 2026).
osteosarcoma (1 paper, 2025). A usually aggressive malignant bone-forming mesenchymal neoplasm, predominantly affecting adolescents and young adults. "To examine whether endogenous expression of IL13RA1-LOR1a can affect the ability of the cells to sense IL-4 or IL-13, we targeted its expression in U2OS osteosarcoma cells, which respond to stimulation by up-regulating CCL26." (PMID 40614216, 2025).
Pruritus (1 paper, 2024). Pruritus is an itch or a sensation that makes a person want to scratch. "The findings suggest a pivotal role of IL-4 and IL-13, along with IL-13RA1, in pruritus pathogenesis in both entities, while IL-13 upregulation in AD is countered by IL-13RA2." (PMID 39126011, 2024).
psoriasis (1 paper, 2012). An autoimmune condition characterized by red, well-delineated plaques with silvery scales that are usually on the extensor surfaces and scalp. "One report, for instance, has commented that intensity of immunohistochemical IL-13Rα1 staining tends to be stronger in psoriasis lesions that are larger in size, which potentially, may reflect differential activation of IL-13-sensitive pathways across stages of plaque development." (PMID 22479649, 2012).
pulmonary TB (1 paper, 2016). "To validate our results in human TB patients, we here determined the association of distinct variants of the IL4, IL13, IL4RA, IL13RA1, and IL13RA2 genes with cavity formation in a large Ghanaian cohort of HIV-negative individuals with newly diagnosed pulmonary TB." (PMID 26977119, 2016).
scleroderma (1 paper, 2012). Scleroderma is a rare autoimmune connective tissue disorder characterized by abnormal hardening of the skin and, sometimes, other organs. "Additionally, these cells also express IL13Ra1, which is upregulated in GVHD, suggesting both that they are competent to respond to IL13, and increased IL13Ra1 was associated with an IL13-driven expression signature in murine GVHD and human scleroderma." (PMID 22957096, 2012). "Additionally, we have previously observed that expression of IL13Ra1 correlated with an IL13 response signature in both a mouse model of sclerodermatous GVHD and in human scleroderma." (PMID 22957096, 2012).
synovitis (1 paper, 2020). Inflammation of a synovial membrane. "The therapeutic effects of IL13Rα1 on the severity of type II collagen-induced arthritis (CIA) in DBA-/1 mouse model were evaluated by scoring synovitis, hyperplasia, cartilage degradation, and bone destruction." (PMID 32771038, 2020).
type 2 diabetes (1 paper, 2025). "We also found that genetic variants of human IL13RA1 were associated with BMI and type 2 diabetes." (PMID 40198135, 2025).
tumor (32 papers, 2014 to 2025). "There remains limited understanding of how IL13-ligand CAR design impacts the activity and selectivity for the intended tumor-associated target IL13Rα2 versus the more ubiquitous unintended target IL13Rα1." (PMID 36968221, 2023). "IL-13Rα1 and IL-13Rα2 are known tumor-associated antigens and recent clinical trials have explored inoculation with IL-13Rα2 and other tumor associated antigens as an immunotherapy." (PMID 29621254, 2018). "Notably, IL13Rα1-overexpressing PCa cells were more susceptible to apoptosis and exhibited reduced tumor growth after exposure to the HK2 inhibitor, 2-deoxy-D-glucose (P < 0.01)." (PMID 34652890, 2021). "One possible explanation might be that IL4Rα/IL13Rα1 are involved in tumorigenesis in association with nuclear proteins related to tumor biology." (PMID 33419470, 2021). "The IL13Rα1-positivity was significantly associated with higher tumor stage (p = 0.019)." (PMID 31540495, 2019). "Especially, IL4Rα+IL13Rα1+ subgroup of CCRCC significantly associated with larger tumor size, higher tumor stage, and lymph node metastasis, and predicted a 3.2-fold greater risk of death of CCRCC patients compared with IL4Rα−IL13Rα1−/IL4Rα−IL13Rα1+/IL4Rα+IL13Rα1− subgroups." (PMID 31540495, 2019). "In addition, higher expression of IL4Rα and IL13Rα1 were associated with advanced clinicopathological factors of STSs such as higher tumor stage, cancer metastasis, higher histologic grade, increased mitosis, and tumor necrosis." (PMID 33419470, 2021). "However, recent reports have suggested that the high expression of IL4Rα and IL13Rα1 in tumor tissue might be associated with tumorigenesis in several kinds of tumor." (PMID 31540495, 2019). "Our ongoing studies will address the possibility that our newly engineered anti‐IL‐13 Rα2 construct will improve tumour specificity and reduce potential for off target effects due to expression of IL‐13 Rα1 on normal tissues." (PMID 38685487, 2024). "These cytokines primarily signal through the type II IL-4R, composed of IL-4Rα and IL-13Rα1, which is expressed in a wide array of epithelial tumor cells." (PMID 38519926, 2024). "By binding to its receptors IL-13Ra1 and IL-13Ra2, it activates downstream signaling cascades, influencing the proliferation, inhibition, or apoptosis of certain tumor cells." (PMID 38519926, 2024). "To interrogate the selectivity of the C4 and D7 mutein CAR T cells in vivo, we investigated the antitumor activity of the CAR T cells in xenograft models using IL13Rα1-expressing tumor cells." (PMID 35939683, 2022). "To investigate the influence of IL13Rα1 expression in healthy tissue on the trafficking of IL13-variant CAR T cells, we conducted in vivo biodistribution studies in a bilateral tumor model." (PMID 35939683, 2022). "Previous studies reported that IL-13Rα1 can restrict tumor progression; IL-13 binding to IL-13Rα1 activates Stat6 which promotes caspase-3 mediated apoptosis." (PMID 33591997, 2021). "Compared to a vector control (VCtrl), ectopic expression of IL13Rα1 significantly inhibited (P < 0.01) the growth of C42B tumor xenografts under both normal and castrated conditions." (PMID 34652890, 2021). "Another interesting finding was that low IL-13Rα1 expression corresponds with new tumor events in ACC patients." (PMID 33591997, 2021). "Regarding a possible treatment, we showed that ectopic expression of IL13Rα1 plus HK2 inhibition additively inhibited tumor growth under castration resistance conditions." (PMID 34652890, 2021). "IL13Rα1 overexpression promoted apoptosis and inhibited tumor growth under androgen-deprived or castrated conditions (P < 0.01)." (PMID 34652890, 2021). "Our data identified a tumor suppressor role for IL13Rα1 in preventing the resistance of PCa cells to apoptosis during androgen deprivation by inhibiting glycolysis." (PMID 34652890, 2021).
tumor (continued). "Related genes that are involved in the formation of IL-13R complex (IL-13Rα1 and IL-4R) and program cell death ligand (PD-L1), as a control, were also evaluated with respect to patient age, hormone production, new tumor events, and tumor metastasis." (PMID 33591997, 2021). "In human CCRCC tissue, the expression of IL4Rα and IL13Rα1 were seen in both the cytoplasm and nuclei of tumor cells." (PMID 31540495, 2019). "In DIPG tissues, transcript-level analysis found significant expression of IL-4, IL-13, and IL-13Rα1/2, with strong differential expression of IL-13Rα1/2 in tumor versus normal brain." (PMID 29621254, 2018). "In various types of cancer including GBM, IL-4Rα, and IL-13Rα1, they have been shown to be overexpressed and promote tumor proliferation, cell survival, and metastasis." (PMID 28752098, 2017). "IHC staining of a representative normal, stage I, II, III, and IV tumor for IL-4Rα, IL-13Rα1, and IL-2RγC chain demonstrated an increasing trend of IL-4Rα immunostaining." (PMID 25208941, 2014). "IHC analyses from tumor and adjacent specimens corroborated the mRNA results and demonstrated overexpression of IL-4Rα and IL-13Rα1 in tumor compared to surrounding tissue." (PMID 25208941, 2014). "We found that patients highly expressing the top 20 signature genes of IL13RA1+ E02 had shorter overall survival, further confirming their functions in tumor angiogenesis; however, signature genes of VCAM1+ E06 were not significantly correlated with clinical outcomes of patients with HGSOC." (PMID 37488416, 2023). "However, in Winn assays, C4 displayed the least inhibition to IL13Rα1-expressing A549 tumor xenografts." (PMID 35939683, 2022). "Together, these data indicated that IL13Rα1 played a tumor suppressor role in PCa." (PMID 34652890, 2021). "In addition, we noted that survival from a new tumor event was related with an elevated IL-13Rα1 expression." (PMID 33591997, 2021). "However, new tumor events occurred significantly more frequently in ACC subjects with low (64%) versus medium (34.6%) IL-13Rα1 expression (p = 0.05)." (PMID 33591997, 2021). "In conclusion, this study demonstrated that the expression of IL4Rα and IL13Rα1, especially when highly expressed in nuclei, were associated with advanced clinicopathological factors of STS such as higher tumor stage and high histologic grade, and predicted shorter survival of STS patients." (PMID 33419470, 2021). "Likewise, IL13Ra1 transcripts were detectable in all examined tumor samples and their expression level was the lowest in colonic samples, both cancerous and non-cancerous." (PMID 32512917, 2020). "In addition, tumor tissue from ESCC patients had significantly lower IL13Ra1 and IL13 expression as compared to GC patients." (PMID 32512917, 2020). "Suppression of IL4 and IL13 as well as IL4Rα and IL13Rα1 might be tumor-suppressive especially in poor prognostic group of cancers expressing both IL4Rα and IL13Rα1 as like IL4Rα+IL13Rα1+ subgroup of CCRCC." (PMID 31540495, 2019). "However, dupilumab may promote tumor progression by blocking IL-13Rα1 and then increasing IL-13 binding to IL13Rα2, thus promoting tumor progression in some tumors, especially CTCLs." (PMID 39758935, 2025). "Consistent with the expression of Il13ra1 and Il17rb on tuft cells, IL25 or IL13 stimulation of tumor organoids increased their size, while treatment of organoids with an α-IL25 neutralizing antibody resulted in reduced organoid growth." (PMID 37898600, 2023). "Ultimately, we identified specific populations of stromal cells playing important roles in tumor progression, such as DES+ mesothelial cells in ascites and IL13RA1+ endothelial cells in tumor site." (PMID 37488416, 2023). "Further deciphering the transcriptional trajectories of endothelial cells using PAGA, we found that IL13RA1+ E02 and VCAM1+ E06, two major endothelial cell clusters in tumor tissues, exhibited unique features." (PMID 37488416, 2023).
tumor (continued). "Following tumor growth kinetics over 60 days, the WT CAR T cells ablated engraftment of IL13Rα1-expressing tumors." (PMID 35939683, 2022). "The results showed that CACNA1H, IL13RA1, NUP43, PGK1, and SDC1 were highly expressed in tumor samples, while expression of AK3 was significantly decreased." (PMID 34600547, 2021). "IL4R is composed of several distinct chains, on several tumor cells IL4Rα and IL13Rα’ chains are expressed and bind IL4, while in many solid tumor IL13 binds the chains IL-4Rα and IL13Rα1 and IL13Rα2." (PMID 32957689, 2020). "Paired comparison of IL-13 in adjacent and tumor colonic tissue showed significantly higher protein concentration and IL13 transcript number in tumors but similar expression level of IL13Ra1 transcripts." (PMID 32512917, 2020). "IL13RA1, in conjunction with IL4R, forms the type II IL4 receptor on tumor cell membranes." (PMID 39941924, 2025). "Using the tumor line A549, which endogenously expresses IL13Rα1, but not IL13Rα2, we found that the IL13-28ζ CAR T cells exhibited the most off-target–mediated degranulation, activation marker expression, in vitro cytotoxicity, and proliferation." (PMID 36968221, 2023). "In coculture of CAR T cells with IL13Rα1-expressing tumor cells (A549 and HT1080-IL13Rα1) at a 1:1 E:T ratio, WT and E12Y induced significantly more surface expression of CD107a and intracellular expression of IFN-γ than C4 and D7 (P < 0.05 for all comparisons)." (PMID 35939683, 2022). "Given the association of the pro-tumoral IL-25-ILC2 axis with MDSCs, and the expression of Il4ra and Il13ra1 by M-MDSCs, we sought to investigate whether ILC2-derived IL-4 and IL-13 promote MDSC function to suppress anti-tumor immunity." (PMID 35658010, 2022). "Therefore, when considering the oncogenic role of JAK2 and tumor-suppressive role of FOXO3, nuclear localization of IL4Rα/IL13Rα1 exerts its role by involving JAK2-FOXO3 interaction in the progression of STSs." (PMID 33419470, 2021). "The differences in both IL13 and IL13Ra1 transcripts between adjacent and tumor tissue were non-significant." (PMID 32512917, 2020). "Mechanistically, IL4Rα and IL13Rα1 could increase JAK2 signaling pathway and suppress tumor-suppressive activity of FOXO3." (PMID 31540495, 2019). "To characterize the mutation status and gene expression levels of the cytokines IL-4 and IL-13, their receptors IL-4Rα, IL-13Rα1/2, and the oncogenes c-Met and EGFR, we performed exome and RNA-seq analysis on DIPG tissues (38 tumor exome, 26 normal exome, 28 tumor RNA, 18 normal RNA)." (PMID 29621254, 2018). "In CRC clinical samples, we also find IL-13Rα1 expression level but not IL-13Rα2 is higher in CRC tissues when compared with adjacent non-tumor tissues at the mRNA levels." (PMID 27533463, 2016). "The IL-13Rα1 staining was weak to modest (<1+) in tumor and normal/noncancerous specimens suggesting weak or no overexpression of IL-13Rα1 chain in BC specimens." (PMID 25208941, 2014). "In contrast, IL-13Rα1 mRNA was expressed but at lower levels of RFUs of 22–28% in tumor specimens compared to 8–10% in normal/noncancerous bladder specimens (P ≤ 0.001)." (PMID 25208941, 2014). "Decreasing the binding affinity for IL13Rα1 to the micromolar range had the desired effect in in vitro tumor treatment assays, with both C4 and D7 CAR T cells showing diminished responses relative to WT and E12Y CAR T cells when exposed to IL13Rα1-expressing cancer cells and plate-bound IL13Rα1." (PMID 35939683, 2022). "Immunohistochemistry and western blotting analyses showed reduced protein expression of CHI3L1, PCNA, cyclin D1, Cdk 6, and MMP‐9, but the expression of cleaved caspase‐3 was increased; however, IL‐13Rα1 and IL‐13Rα2 levels were not changed in K284‐treated lung metastasis tumor tissues." (PMID 34758182, 2022). "Also, among the 17 ACC patients with tumor metastasis, the level of IL-13Rα1 expression did not influence the survival rate." (PMID 33591997, 2021).
tumor (continued). "A total of 28 specimens, which consisted of 16 tumor specimens and 12 normal/noncancerous bladder specimens obtained from CHTN were analyzed for mRNA expression of IL-4Rα, IL-13Rα1, and IL-2Rγc by real-time RT-PCR assay." (PMID 25208941, 2014).